IDO1 (indoleamine 2,3-dioxygenase 1)
Diseases named in the same sentence as IDO1 in open-access papers (continued):
Sharing a sentence is not in itself a finding about the gene and the disease.
viral infections (53 papers, 2011 to 2025). "Although these findings do not establish direct causality, they are consistent with previous reports on IDO1-driven immune modulation in viral infections and warrant further investigation through enzyme activity or metabolomics assays." (PMID 40459260, 2025). "We also found increased expression of other co-inhibitory molecules (BTLA, FASLG, FAS, and IDO1) that are associated with the regulation of T-cell exhaustion during chronic viral infection." (PMID 32731586, 2020). "To date, IDO1 expression and activity in alveolar macrophages have been reported in a mouse model of pneumonia caused by allogeneic hematopoietic stem cell transplantation or viral infection." (PMID 38221627, 2024). "Viral infection activates AhR through an IDO1-AhR-IDO1-positive feedback loop, which eventually causes upregulation of downstream effectors, such as TCDD-inducible PARP (TiPARP), and enhances the expression of cytokines (e.g., interleukin IL-1β, IL-10, and TNF-α)." (PMID 34621138, 2021). "Although the viral infection itself accelerated the development of diabetes, the presence of stimulated iNKT cells during this time caused infiltrated macrophages to express several suppressive enzymes, among which IDO1 was sufficient to inhibit anti-islet T cells response and to prevent T1DM." (PMID 34576041, 2021). "For some viral infections high IDO1 activity represents a main cause of immune unresponsiveness during the initial immune responses that aims to eradicate pathogens and downregulation of the short-term immunosuppressive regulatory effects of IDO1 should improve this short-term immune response." (PMID 34163018, 2021). "Clinically, IDO1-driven Trp breakdown, reflected by altered Kyn/Trp ratios, correlates with immune suppression and poor prognosis in tumors and viral infections." (PMID 40459260, 2025). "In virus infection, inhibiting IDO-1 with 1-MT intensified inflammatory reaction via secreting proinflammatory cytokine." (PMID 36517670, 2023). "The coinhibitory molecules TIM3, LAG3 and IDO1 have been poorly examined along porcine viral diseases." (PMID 36713151, 2022). "The transformation of Trp in Kyn can be catalyzed by TDO or IDO-1, but in the immune system, the expression of IDO-1 is prevalent and can be induced by viral infections and IFN-γ." (PMID 35203299, 2022). "The upregulation of IDO-1 has been described in other viral infections, such as hepatitis C infection." (PMID 35203299, 2022). "The strong IFN-γ release early after viral infection upregulates IDO1 expression to downregulate the virus-induced inflammation." (PMID 34576041, 2021). "IDO-1 is a master regulator of the Kyn pathway and downstream regulator of interferon signaling, which is activated during viral infection." (PMID 34621138, 2021). "Other immune checkpoints, such as cytotoxic T-lymphocyte associated protein 4 (CTLA4), lymphocyte activating 3 (LAG3) and indoleamine 2,3-dioxygenase 1 (IDO1) have been also studied in immunosuppressive viral diseases such as PMWS and CSF." (PMID 34046040, 2021). "RSAD2 and IDO1 are mainly triggered by interferons as part of the concerted counteraction against viral infection." (PMID 32849329, 2020). "IFN-mediated IDO1 upregulation upon various acute and chronic viral infections has been demonstrated by many research groups." (PMID 29342871, 2018). "The increase of IDO1 expression in HCC is probably induced either by the inflammation stimulated by viral infection, or by immune activation of CD8+NKG2D+ cells." (PMID 28701757, 2017). "IDO1 expression also plays an important role during viral infections, such as HIV, influenza, Epstein–Barr, HBV, and HCV." (PMID 28066439, 2016). "In the current study we show that acute influenza (IAV) and chronic retroviral (MuLV) infections enhanced mechanical pain sensitivity and that IDO1 ablation alleviated these responses to virus infection." (PMID 27168185, 2016).
viral infections (continued). "Particularly, the regulation of type I interferons (IFNs) production via IDO1 in virus infection is discussed." (PMID 23476103, 2013). "Viral infection triggers the stimulation of Toll-like receptors (TLRs), which induce the production of kynurenine by degrading tryptophan and activating indoleamine 2,3-dioxygenase (IDO1)." (PMID 40472053, 2025). "IDO1 overactivity has also been observed in the course of viral diseases." (PMID 39120289, 2024). "High expression of IDO1 in bat neutrophils was observed in a single-cell transcriptome analysis study of viral infection response in bats, which may play an important role in limiting inflammation in the context of neutrophil-activated conditions." (PMID 36861979, 2023). "It has been already reported that IDO1 restricts many viral infections." (PMID 35883685, 2022). "IDO1 is an immune regulatory enzyme, induced at sites of inflammation, capable of modulating the immune cell activation, and preventing the viral spread in some viral infections." (PMID 36713151, 2022). "Furthermore, we have also shown that the participation of IDO1 in the genesis of viral infections incites pain hypersensitivity." (PMID 36227694, 2022). "Notably, IDO1 staining was predominantly found in endothelial cells, which suggests a relationship between viral infection and changes in pulmonary vascular response." (PMID 33298930, 2020). "Together, these data suggest that the observed systemic increase of kynurenine during homeostasis and upon viral infection of Tdo2-deficient animals is unlikely to be due to altered hepatocyte-intrinsic activity of IDO1 or IDO2." (PMID 33045014, 2020). "This is because the promoter region of IDO1 gene contains two interferon-stimulated response elements (ISREs) and three IFNγ-activated sites that respond to interferons that are often produced to control viral infections." (PMID 29342871, 2018). "First, host cells increase IDO1 expression in response to viral infections." (PMID 29342871, 2018). "However, in viral infections, the induction of IDO1 by IFN seems to be generally harmful by the establishment of an immunotolerogenic microenvironment." (PMID 28066439, 2016). "IDO1 activities in various tissues are induced by several cytokines after viral infection." (PMID 23476103, 2013). "Both in the context of virus infection and cancer, sustained IFN-I signature is associated with chronic inflammation along with increases in immune checkpoint molecules, such as PD-1, PD-L1, IL-10 and IDO1 (indoleamine 2,3 dioxygenase 1), resulting in immunosuppression." (PMID 37686559, 2023). "Other human viral infections, such as herpes simplex virus type 2 (HSV-2) and measles virus (MV) were sensitive to IDO-1-induced tryptophan depletion." (PMID 35456119, 2022). "Thus transient and sustained increase in pain sensitivity manifested during acute IAV or chronic MuLV infections, respectively, and these responses to virus infection depended on IDO1 gene expression but were not linked to changes in virus infection kinetics or host immunopathogenesis." (PMID 27168185, 2016). "As IFNs play an important role in defense against viral infections, and IDO1 is specifically induced by IFNs, we investigated the response of BALB/c IDO1-KO mice to an infection with MCMV." (PMID 26914138, 2016). "These experimental results demonstrate that IDO1 can be induced by double-stranded RNA and suggests a therapeutic function for PIC in human viral infections." (PMID 26378585, 2015). "Furthermore, 14 proteins that were upregulated after virus infection—including TNFaIP3, HNRNPH2, RSAD2, ISG20, IDO1, and KCNN4—also exhibited significantly increased mRNA levels relative to uninfected cells (p < 0.05)." (PMID 36423196, 2022). "This suggests that exogenous viral infection in tumor (e.g., EBV, HPV, and HCV) is associated with the over-expression of IDO-1 and sometimes IDO-2 but not TDO-2." (PMID 34367262, 2021).
viral infections (continued). "The physiological role of IDO2 remains unclear, and unlike IDO1, its expression is not induced by virus infection or the presence of IFNγ." (PMID 26378585, 2015). "However, the role of IDO1 in vivo after parasitic or viral infection is not fully understood." (PMID 23476103, 2013).
hepatocellular carcinoma (51 papers, 2011 to 2025). A malignant tumor that arises from hepatocytes. "Conversely, other studies indicated the tumor IDO1 expression was associated with good prognosis in renal carcinoma and hepatic carcinoma." (PMID 32733806, 2020). "In contrast, patients with hepatocellular carcinoma and high levels of IDO1 exhibit a good prognosis." (PMID 39371092, 2024). "The correlation between H2S-generating enzyme CSE and IDO1 was investigated by immunostaining and heatmaps analysis in clinical specimens and tissue arrays of hepatocellular carcinoma (HCC) patients." (PMID 30777103, 2019). "In summary, our study provides important new insights into the collaborative action of immune cells that is exercised to up-regulate immunosuppressive IDO1 in hepatoma cells." (PMID 26895379, 2016). "In addition, Abrine can target IDO1 to inhibit tumor cell immune escape and enhance anti-PD-1 immunotherapy in hepatocellular carcinoma." (PMID 38439022, 2024). "H22 cells are IDO1 expressing and highly tumorigenic hepatocellular carcinoma cells." (PMID 30777103, 2019). "In addition, IDO1 expression in hepatocellular carcinoma specimens and in endothelial cells of renal cell carcinoma positively correlated with progression-free survival and long-term survival, respectively." (PMID 21625531, 2011). "To validate the clinical relevance of IDO1 in pathogenesis of HCC, we analyzed data from the liver hepatocellular carcinoma (LIHC) cohort from The Cancer Genome Atlas (TCGA) database retrieved and processed via the UALCAN portal." (PMID 34769098, 2021). "IDO1 is highly expressed in M2 macrophages in the tumor microenvironment in 58% of hepatocellular carcinoma (HCC) cases." (PMID 34943977, 2021). "Analysis of The Cancer Genome Atlas Liver Hepatocellular Carcinoma (TCGA LIHC) dataset in the current study revealed a significant correlation between IDO1 expression and HCC." (PMID 34769098, 2021). "H2S suppresses IDO1 expression and exhibits immunotherapeutic efficacy in H22 hepatocellular carcinoma (HCC)-bearing mice." (PMID 30777103, 2019). "The ISX expression strike enhanced the levels of tryptophan catabolic enzymes, indoleamine 2,3-dioxygenase 1 (IDO1), tryptophan 2,3-dioxygenase, and immune checkpoints regulators PD-L1 and B2-7 (CD86) in hepatocellular carcinoma cells." (PMID 41417109, 2025). "Recent studies have shown that IDO1 expression positively correlates with CD8+ T cell populations amongst tumor-infiltrating lymphocytes in rectal carcinoma, hepatocellular carcinoma, and early-stage cervical cancer." (PMID 38540186, 2024). "In hepatocellular carcinoma (HCC) patients, the expression of IDO1 is negatively correlated with the expression of CSE." (PMID 36929586, 2023). "Dang Yang ‘s team found that H2S can down-regulate IDO1 expression by blocking NF-κB and STAT3 pathways and inhibit IDO1 activity through H2S/NO cross-talk, which has an immunotherapeutic effect on H22 hepatocellular carcinoma (HCC) tumor-bearing mice." (PMID 36558139, 2022). "However, whether immune cells could influence the IDO1 in human hepatoma cells remains unclear." (PMID 26895379, 2016). "Further, the KP enzyme kynurenine monooxygenase (KMO), active downstream of IDO1, has been shown to play a critical role in human hepatocellular carcinoma and to be independent of IDO1 activity." (PMID 33109232, 2020). "Collectively, these data revealed that immune cells are required for the induction and maintenance of IDO1 protein in those human hepatoma cells without constitutive IDO1 expression." (PMID 26895379, 2016). "Unexpectedly, IDO1 expression were not detectable in all of the 6 human hepatoma cell lines grown in vitro, suggesting that additional factors within the tumor milieu are required for inducing IDO1 in tumor cells." (PMID 26895379, 2016). "Human hepatoma cells HepG2, which did not express IDO1 in vitro, were subcutaneously implanted into non-obese diabetic/severe combined immunocompromised (NOD/SCID) mice." (PMID 26895379, 2016).
hepatocellular carcinoma (continued). "STAT1 was significantly positively correlated with PD1 (r = 0.448), PD-L1 (r = 0.444), CTLA-4 (r = 0.436), FGFR2 (r = 0.354), FGFR3 (r = 0.36), and IDO1 (r = 0.387) in HCC, suggesting that targeting STAT1 may improve the efficacy of immunotherapy for hepatocellular carcinoma." (PMID 35646925, 2022). "First, 6 human hepatoma cell lines we examined did not constitutively express IDO1." (PMID 26895379, 2016). "In vitro culture, human hepatoma cell lines did not constitutively express IDO1." (PMID 26895379, 2016). "By contrast, in hepatocellular carcinoma, CAFs secrete IL-6 to mediate STAT3 activation, convert normal DCs into cells with high IDO1 expression and educate them to acquire a tolerogenic phenotype." (PMID 35681736, 2022). "Next, using the tissue arrays of HCC patients (158 cases) and metastatic hepatocellular carcinoma (MHCC) patients (158 cases), we further verified the negative relation between CSE expression and IDO1 expression by some statistical analysis and empirical tests." (PMID 30777103, 2019).
Autoimmunity (50 papers, 2011 to 2026). The occurrence of an immune reaction against the organism's own cells or tissues. "Many studies have shown that IDO1 is closely associated with a variety of human diseases, including inflammatory diseases, microbial infections, autoimmunity, tumors and psychiatric disorders." (PMID 37509627, 2023). "Low expression of IDO1 in response to IFN-γ and degradation of IDO1 have been suggested as the mechanisms underlying autoimmunity." (PMID 37394584, 2023). "Forced IDO1 expression rescues both activities – enzymic and signalling – of the protein, thus providing proof-of-principle that a global IDO1 defect predisposes NOD mice to autoimmunity." (PMID 25215657, 2014). "Thus, IDO2 seems to be the dominant player in the pathogenic autoantibody-mediated autoimmunity through an IDO1-independent mechanism." (PMID 34576041, 2021). "Furthermore, C24:1 sulfatide has been shown to induce transcription of the gene encoding indoleamine 2,3-dioxygenase 1, an important regulator of autoimmunity with reduced expression in individuals with newly diagnosed type 1 diabetes." (PMID 31410530, 2019). "Aside from the activation of T‐reg cells and release of IL‐2, some enzymes (for instance, IDO1 and retinaldehyde dehydrogenase) play parts in the inhibition of Th1‐based autoimmunity." (PMID 39150219, 2024). "In this section, we focus on how the IDO1-AHR axis in epithelial cells regulates tissue inflammation or autoimmunity mediated by T cells." (PMID 37394584, 2023). "Accumulating evidence supports the role of the IDO1-AHR axis in the maintenance of tolerance relevant to autoimmunity." (PMID 37394584, 2023). "IDO1 is induced in the context of inflammation and is involved in autoimmunity, chronic infection, granulomatous diseases, and cancer." (PMID 36296342, 2022). "IDO1 is involved in several pathological conditions, including atherosclerosis, autoimmunity, infections, and cancer." (PMID 34769098, 2021). "Sustained tissue re-modeling and local inflammation enhance cell death and dying cells promote potent tolerogenic responses, in part because DNA from dying cells is sensed to induce IDO1 and suppress immunity and autoimmunity." (PMID 32625215, 2020). "This is consistent with enhanced T cell responses reported when IDO1 was deleted in other models, including induced models of cancer and T cell-mediated autoimmunity." (PMID 32973768, 2020). "For example, in the EAE model of MS in mice, IDO activity was elevated in CNS tissues during EAE induction but STING agonists treatments to induce IDO in peripheral lymphoid tissues and suppress autoimmunity abolished IDO1 expression in the CNS." (PMID 29163470, 2017). "Members of the Tumor Necrosis Factor (TNF) receptor family have been shown to stimulate DC maturation or modulate peripheral tolerance in autoimmunity by upregulation of IDO1." (PMID 26881431, 2016). "Initially identified as a counter-regulatory mechanism in acute inflammation 40 and for its role in fetomaternal tolerance 41, IDO1 is also critical in balancing inflammation with tolerance in transplantation, cancer and autoimmunity 17,42–45." (PMID 25215657, 2014). "In autoimmunity, IDO1 and TDO impaired T cells and antigen-presenting cells." (PMID 37540213, 2023). "The recent in vivo studies performed on the models of autoimmunity suggest that IDO2 may play a distinct from IDO1 role in the B cell-mediated autoimmunity." (PMID 34576041, 2021). "Additionally IDO-1 and various KP metabolites have been shown to ameliorate autoimmunity and to promote immune tolerance." (PMID 32604956, 2020). "IDO1 is believed to play an important role in acquired tolerance, nevertheless, IDO1-deficient mice do not develop spontaneous lethal autoimmune disorders." (PMID 26914138, 2016).